JAK3 (Janus kinase 3)
Diseases named in the same sentence as JAK3 in open-access papers (continued):
Sharing a sentence is not in itself a finding about the gene and the disease.
colon carcinoma (6 papers, 2015 to 2025). "Therefore, deregulation of Jak3 expression has been linked to colon cancer." (PMID 33814980, 2021). "Jak3 plays an essential role in epithelial cell migration in response to IL-2, and a correlation can be made to metastatic potential of colon cancer cells." (PMID 33814980, 2021). "For example, JAK3 was constitutive activated in colon carcinoma tumors and inhibiting JAK3 expression leads to apoptosis and cell cycle arrest in colon carcinoma cells 20; JAK3 was aberrantly upregulated in non-small cell lung cancer cells and associated with cancer progression." (PMID 39991585, 2025). "Functional Jak3 is expressed in human intestinal enterocytes including colon cancer cells." (PMID 33814980, 2021).
diabetes (6 papers, 2011 to 2025). "Inhibition of JAK3 has been shown to protect against diabetes onset in mouse models, highlighting its importance in diabetes pathogenesis." (PMID 40597598, 2025). "We have previously reported the upregulation of Jak3 at three months of untreated diabetes in the STZ rat model and the failure of insulin to prevent upregulation of Jak3 suggests that insulin therapy is insufficient to prevent some aspects of retinal inflammation with diabetes." (PMID 21575160, 2011).
lupus (6 papers, 2019 to 2025). "A recent report indicated that tofacitinib, a JAK inhibitor that mainly inhibits JAK3, reduced circulating NETs in lupus patients." (PMID 36319843, 2022).
lymphopenia (6 papers, 2013 to 2025). Reduction in the number of lymphocytes. "Jak3-deficient mice had severe B cell and T cell lymphopenia." (PMID 37510940, 2023). "Taken together, we here describe for the first time JAK3 deficiency due to a hypomorphic JAK3 mutation and with somatic chimerism, causing a phenotype of T-cell deficiency evolving into predominant CD4 lymphopenia." (PMID 25205547, 2014). "Taken together, JAK3 inhibition may be related to the JAKi-induced lymphocytopenia." (PMID 37510940, 2023). "This would suggest that the JAK3 Cys905Ser protein is expressed and is active as the knockin mice do not exhibit the severe lymphopenia seen in JAK3 knockout animals." (PMID 33980892, 2021). "Jak3 -/- mice display T and B cell lymphopenia without effects on myeloid lineage cells (i.e., Gr-1 positive granulocytes, erythroid cells and Mac-1 monocytes)." (PMID 24170986, 2013).
non-small cell lung carcinoma (6 papers, 2017 to 2025). A group of at least three distinct histological types of lung cancer, including non-small cell squamous cell carcinoma, adenocarcinoma, and large cell carcinoma. "JAK3 was regularly found upregulated in various cancer cells, such as colon and non-small cell lung cancer." (PMID 39991585, 2025). "JAK3 and STAT3 genes had been reported to be different among the NPC cell lines, and in other types of cancer including natural killer T cell lymphoma, and non-small cell lung cancer." (PMID 39769218, 2024).
pancreatic cancer (6 papers, 2012 to 2025). "IL2RG encodes for a subunit of the interleukin-2 receptor complex, which regulates T-cell function, was previously linked to poorer prognosis in gastric cancer, and IL2Rγ/JAK3 signaling has been shown to contribute to pancreatic cancer proliferation in vivo." (PMID 39796775, 2025). "In 2017, Ayars and al, using CRISPR-mediated knockout of IL2RG in orthotopically implanted pancreatic cancer cells, observed a reduction in tumor growth in mice and decreased JAK3 in orthotopic tumors." (PMID 40096084, 2025). "CRISPR-mediated knockout of IL2RG in orthotopically implanted pancreatic cancer cells resulted in attenuated tumor growth in mice and reduced JAK3 expression in orthotopic tumors." (PMID 29137350, 2017). "In this paper, we examined the effects of EGCG on STAT3 signaling in human pancreatic cancer cells, and also assessed the interactive effects of EGCG with gemcitabine or JAK3 inhibitor CP690550 on their therapeutic potential." (PMID 22348037, 2012). "Here, we examined the effects of epigallocathechin gallate (EGCG) on STAT3 signaling in pancreatic cancer cells, and assessed the therapeutic potential of EGCG with gemcitabine or JAK3 inhibitor CP690550 (Tasocitinib) for the treatment and/or prevention of pancreatic cancer." (PMID 22348037, 2012).
renal fibrosis (6 papers, 2016 to 2025). A final common manifestation of a wide variety of chronic kidney diseases characterized by glomerulosclerosis and tubulointerstitial fibrosis. "Studies have demonstrated the involvement of both the adiponectin/APK and JAK3/STAT6 signalling pathways in the development of experimental renal fibrosis and collagen production by cultured mouse cells undergoing MMT." (PMID 39445007, 2024). "This evidence supports that JAK3/STAT6 signaling takes a crucial part in renal fibrosis via regulating the MMT." (PMID 35990655, 2022). "STAT6-deficient mice or mice treated with a JAK3 inhibitor (CP690,550) had fewer accumulations of bone marrow-derived fibroblasts in the experimental obstructed kidney model and developed less renal fibrosis." (PMID 35990655, 2022). "In addition, recent studies have shown a role for adiponectin/AMPK and JAK3/STAT6 signaling pathways in the development of experimental renal fibrosis and in collagen production by cultured mouse monocytes, providing new potential therapeutic targets in addition to TGF-β/Smad3 signaling." (PMID 27906172, 2016). "The remaining signalling pathways mediating renal fibrosis are STING/TBK1, IL-4Ra/STAT6, Jmjd3/IRF4, STAT6/PPARα, SETD7, NKT/IL-4, BRP-39, STAT-1/TREM-1, MMP-9/Akt, adiponectin/APK, and JAK3/STAT6." (PMID 39445007, 2024). "We have also shown that JAK3 inhibitor treatment, or the genetic deletion of STAT6, inhibits M2 macrophage populations and monocyte-to-fibroblast transition, thereby suppressing renal fibrosis in a mouse model of obstructive nephropathy." (PMID 34831280, 2021). "We have recently shown that JAK3/STAT6 plays a crucial role in the activation of bone marrow-derived fibroblasts and development of renal fibrosis in obstructive nephropathy." (PMID 34512669, 2021). "We have showed that the IL4Rα/JAK3/STAT6 signaling pathway play an important role in the activation of myeloid fibroblast and the development of renal fibrosis." (PMID 34512669, 2021). "In our previous studies, we have shown that Jak3 inhibition, or the genetic disruption of STAT6, suppresses the accumulation of myeloid fibroblasts and the formation of myofibroblasts in the kidney and inhibits the development of renal fibrosis in mice with obstructive nephropathy." (PMID 34831280, 2021).
T-cell leukemia (6 papers, 2012 to 2023). A malignant disease of the T-lymphocytes in the bone marrow, thymus, and/or blood. "The coexistence of PHF6 and JAK3 mutations in T-ALL patients was frequently noted, but little is known of the mechanism whereby PHF6 mutations promoted JAK3-driven T-cell leukemia." (PMID 36982575, 2023). "In addition, Tasocitinib was also shown to be effective in inhibition of JAK3 and STAT5 activation in peripheral blood mononuclear cells isolated from T-cell leukemia and HTLV-associated myelopathy/tropical spastic paraparesis." (PMID 22916261, 2012). "Interestingly, activating mutations have been detected in the IL7-receptor gene IL7R, the mediating kinase JAK3, and its target protein STAT5B in T-cell leukemia." (PMID 28977998, 2017).
anemia (5 papers, 2020 to 2025). A reduction in the number of red blood cells, the amount of hemoglobin, and/or the volume of packed red blood cells. "Current discovered JAK3 inhibitors have low selectivity, which could cause complications like thrombocytopenia, leukopenia and anemia." (PMID 38095643, 2023). "One crucial disadvantage of these drugs are their side effects, including anemia and thrombopenia, mainly depending on JAK2- and JAK3 inhibition, which prompted us to focus on JAK1 in this preclinical project." (PMID 32194562, 2020).
cervical carcinoma (5 papers, 2016 to 2026). A carcinoma arising from either the exocervical squamous epithelium or the endocervical glandular epithelium. "The JAK1 and JAK3 responses in cervical cancer cells are different from the responses reported for normal lymphocytes." (PMID 27293315, 2016). "As JAK3 is a well-established upstream kinase of STAT5 and has been reported to play a critical role in cervical cancer progression, we modeled ATXN3’s interaction with phosphorylated JAK3 (p-JAK3, Y980)." (PMID 41507147, 2026). "JAK3 alone may be capable of initiating the signals induced by IL-2 even if JAK1 is not activated in cervical cancer cells." (PMID 27293315, 2016). "EPOR is expressed in cervical cancer, and the binding of erythropoietin (Epo) to its receptor induced cell proliferation; such cell response was related to the activation of JAK2, JAK3, STAT3, and STAT5, but not JAK1 and STAT1 in cervical cancer." (PMID 37372319, 2023). "The characteristics of constitutive JAK3 phosphorylation and the lack of JAK1 phosphorylation in cervical cancer cells have been previously documented in transformed and malignant lymphocytes." (PMID 27293315, 2016).
gastric cancer (5 papers, 2012 to 2025). A primary or metastatic malignant neoplasm involving the stomach. "Including JAK1, JAK2, JAK3, and Tyk2, various JAKs are always activated by cytokines to mediate the gastric cancer cells progression, such as JAK1 kinase by IL-10 family cytokines, JAK2 kinase by G-CSF factor, Tyk2 kinase by cytokine IL-23, respectively." (PMID 35734442, 2022). "In the TCGA cohort, gastric cancer (GC) harboring variants in RECQL4, ARID1A, MAGI1, or JAK3 were 4.5% (n = 20), 27.0% (n = 119), 7.5% (n = 33), or 3.8% (n = 17), respectively." (PMID 33328548, 2020). "The pro‐inflammatory IL2/JAK3/STAT5 axis upregulates PIK3CD expression by modulating PIK3CD transcription, then PI3K/Akt signaling is activated and promotes gastric carcinoma growth and migration." (PMID 38545256, 2024).
glioblastoma (5 papers, 2018 to 2024). The most malignant astrocytic tumor (WHO grade IV). "WHI-P131 and PF-956980 JAK3 inhibitors, were researched and found to effectively reduce glioblastoma proliferation rates but not induce cell death." (PMID 38672566, 2024). "In this study, novel pyrimidine compounds, BY4003 and BY4008, were synthesized to target the JAK3/STAT3 signaling pathway, and their therapeutic efficacy and mechanisms of action were evaluated and compared with Tofacitinib in U251, A172, LN428 and patient-derived glioblastoma cells." (PMID 39153914, 2024).
glioma (5 papers, 2020 to 2024). A benign or malignant brain and spinal cord tumor that arises from glial cells (astrocytes, oligodendrocytes, ependymal cells). "Detection of a BRAF V600E mutation next to mutations in NF1 and JAK3 as well as deletions of KIT and PDGFRA led to the diagnosis of a pediatric-type low-grade glioma or ganglioglioma." (PMID 32758285, 2020).
juvenile myelomonocytic leukemia (5 papers, 2016 to 2024). A myelodysplastic/myeloproliferative neoplasm of childhood that is characterized by proliferation principally of the granulocytic and monocytic lineages. "Juvenile myelomonocytic leukemia (JMML) patients with secondary mutations in JAK3 have poor prognosis and clinical outcome." (PMID 29455667, 2018). "Approximately, 85% of juvenile myelomonocytic leukemia (JMML) patients have JAK3 mutations." (PMID 37489294, 2023).
multiple myeloma (5 papers, 2011 to 2022). "The analysis of the whole transcriptome data revealed different expression levels of several genes, such as JAK1, JAK2, JAK3, RAF, IL6R, NCAM (CD56), WHSC1, MCL1, BCL2, and IGF1, which showed myeloma pathogenesis." (PMID 30079703, 2019).
ovarian carcinoma (5 papers, 2018 to 2025). A malignant neoplasm originating from the surface ovarian epithelium. "Examining compounds that target two of the most common ovarian cancer aneuploidies concurrently (4q and 17p), Pf-06651600/ritlecitinib was identified as a potentially effective therapeutic, which disrupts the JAK3-STAT pathway." (PMID 40565600, 2025). "Jiang B reported that miR-217 inhibited tumor-induced M2 macrophage polarization by targeting IL-6 and regulating the JAK3/STAT3 signaling pathway, probably providing an underlying therapeutic target in the treatment of ovarian cancer." (PMID 33392180, 2020). "Ascites-derived lymphocytes from ovarian cancer patients normally expressed JAK3 and STAT5." (PMID 29342108, 2018). "Ovarian cancer exosomes inhibited the expression of key T-cell activation components, CD3-ζ and JAK3, and induced apoptosis." (PMID 40443670, 2025).
T-cell prolymphocytic leukemia (5 papers, 2015 to 2024). A slow-growing type of leukemia (blood cancer) in which too many lymphocytes are found in the bone marrow and/or blood. "Constitutive activation of Jak3 was further confirmed where K563-C565 deletion mutation in Jak3 leads to STAT5 phosphorylation in T-prolymphocytic leukemia." (PMID 33814980, 2021). "For example, in addition to the pathognomonic alterations of the TCL1 gene, T-cell prolymphocytic leukemia (T-PLL) frequently displays point mutations of JAK1 (6.3% of cases), JAK3 (36.4%), and STAT5B (18.8%)." (PMID 38638855, 2024).
anaplastic large cell lymphoma (4 papers, 2014 to 2023). Anaplastic large cell lymphoma (ALCL) is a rare and aggressive peripheral T-cell non-Hodgkin lymphoma, belonging to the group of CD30-positive lymphoproliferative disorders, which affects lymph nodes and extranodal sites. "In vitro, IL-9 was able to stimulate JAK3-dependent survival of ALK+ anaplastic large-cell lymphoma cells and protect thymic lymphoma cells from dexamethasone-induced apoptosis." (PMID 24722378, 2014).
atopic dermatitis (4 papers, 2016 to 2024). "This highlights the critical role of keratinocytes in the initiation and perpetuation of atopic inflammation and suggests that topical inhibitors of JAK3 may be promising when treating inflammatory skin diseases in dogs, like atopic dermatitis." (PMID 37624299, 2023).
depression (4 papers, 2022 to 2024). "Among the relationships we observed, the statistically significantly higher expression of Janus kinase 3 (JAK3) in patients with depressive disorders is noteworthy." (PMID 35407663, 2022). "JAK3 is also connected to the signaling network related to depression." (PMID 35164461, 2022). "Similarly, lipopolysaccharide (LPS), the main component of outer membrane of gram-negative bacteria which knowingly triggers the inflammatory cascade and induces depression in murine models, elevated phosphorylation of JAK3 and STAT3 in the mouse hippocampus." (PMID 35164461, 2022).
inflammatory bowel disease (4 papers, 2016 to 2021). A spectrum of small and large bowel inflammatory diseases of unknown etiology. "As information about the roles of Jak3 in gastrointestinal functions and associated diseases are only just emerging, in the review, we summarize its implications in gastrointestinal wound repair, inflammatory bowel disease, obesity-associated metabolic syndrome, and epithelial cancers." (PMID 33814980, 2021).
metabolic syndrome (4 papers, 2017 to 2022). A cluster of metabolic risk factors for CARDIOVASCULAR DISEASES and TYPE 2 DIABETES MELLITUS. "The JAK3 KO mice were more prone to developing high-fat induced metabolic syndrome than the control mice." (PMID 32413585, 2020). "Jak3-KO mice showed exaggerated changes in comparison to WT mice when placed on a high-fat diet where 65% of the calories came from a fat source, with a high-fat diet appearing to be a promoter of metabolic syndrome in humans." (PMID 33814980, 2021). "Additionally, these Jak3-KO mice also showed a tendency of gaining body weight, a phenotype similar to human metabolic syndrome." (PMID 33814980, 2021).
mycosis fungoides (4 papers, 2020 to 2026). Classical mycosis fungoides is the most common type of mycosis fungoides (MF), a form of cutaneous T-cell lymphoma, and is characterized by slow progression from patches to more infiltrated plaques and eventually to tumors. "JAK3 p.Ala573Val mutation is also reported in Extranodal NK/T-cell lymphoma, nasal type, and mycosis fungoides." (PMID 33260897, 2020).
myelofibrosis (4 papers, 2018 to 2025). A partial or complete replacement of the bone marrow stroma by fibrous tissue. "Baricitinib and Fedratinib, which show selectivity for JAK2 over JAK3, have gained approval for myelofibrosis while Upadacitinib, which has selectivity for JAK1, has obtained approval for the treatment of rheumatoid arthritis." (PMID 33980892, 2021). "Loss of function mutations in JAK3 result in Severe Combined Immunodeficiency Disease (SCID), as do mutations in the common gamma chain receptor which recruits JAK39–11 while activating mutations in JAK2 are a frequent cause of myeloproliferative disorders such as myelofibrosis and polycythaemia." (PMID 33980892, 2021).
NK/T-cell lymphoma (4 papers, 2014 to 2021). "JAK3 mutations are involved in the pathogenesis of NK/T cell lymphoma." (PMID 24722378, 2014). "We hypothesized RNA Polymerase II could be a target as JAK3 was shown to interact with RNA Polymerase II in NK/T-cell lymphoma." (PMID 33466582, 2021).
primary immunodeficiency (4 papers, 2017 to 2025). "Lessons from patients with primary immunodeficiency states reveal that defects, particularly in JAK3, are well known to be associated with severe combined immunodeficiency syndrome, and support a critical role of JAKs in defense against serious and opportunistic infections." (PMID 32974356, 2020). "With the progress of sequencing technology, an increasing number of atypical primary immunodeficiency (PID) patients have been discovered, including Janus kinase 3 (JAK3) gene deficiency." (PMID 29049190, 2017). "With the progress of sequencing technology, an increasing number of atypical primary immunodeficiency (PID) patients have been discovered, including Janus kinase 3 (JAK3) deficiency." (PMID 29049190, 2017).
renal carcinoma (4 papers, 2012 to 2023). A carcinoma arising from the epithelium of the renal parenchyma or the renal pelvis. "miR-29b overexpression in CD8+ T cells of renal carcinoma patients has been found to induce immune dysfunction through down-regulation of JAK3 and MCL-1." (PMID 29579063, 2018). "Alternatively, the residual expression of JAK3 in samples of renal cancer could be explained by the presence of splice variants of JAK3 lacking the kinase activity essentially detected in various human epithelial cancers cells." (PMID 22363690, 2012). "Similar to TDEs, renal cancer TDE-anchored IL-12 (EXO/IL-12) also provides a much smaller reduction in p-STAT5 expression but has the same inhibitory effect on JAK3, but not on JAK2." (PMID 37514090, 2023). "To determine the mechanism by which prolactin promotes ccRCC, we obtained phosphorylation and transcriptome databases of 110 renal cancer patients with CPTAC and found that PRL was positively correlated with p-STAT3 (p = 0.03, rho = 0.326) and p-JAK3 (p = 0.014, rho = 0.812)." (PMID 34539753, 2021).